MUC1 (mucin 1, cell surface associated)
Diseases named in the same sentence as MUC1 in open-access papers (continued):
Sharing a sentence is not in itself a finding about the gene and the disease.
cancer (continued). "In multivariate models, high cytoplasmic MUC1 (> 73.7%) in nodal metastasis remained an independent prognostic factor for a low 5‐year cancer‐specific survival in all models except the model with distant metastasis (M), indicating its potential utility as an independent prognostic factor." (PMID 41332218, 2025). "MUC-1 is overexpressed in many cancers and, under stress, MUC-1-N is shed into the extracellular space and MUC-1-C is released into the cytoplasm where it may function in oncogenic cell signaling." (PMID 40148706, 2025). "Research has demonstrated that high-level expression of MUC1, through its involvement in the NF-κB and MAPK signaling pathways, could activate the EGFR signaling cascade, which linked to cancer stem cell characteristics." (PMID 40655139, 2025). "TAAs are unmutated self-proteins on cancer cells, such as MUC1 and carcinoembryonic antigen (CEA)." (PMID 40547025, 2025). "Additionally, the influence of MUC1 on shaping the environment and its probable involvement in maintaining cancer stem cells highlights its significance in understanding cancer biology." (PMID 40699746, 2025). "However, this variability in expression and glycosylation patterns contributes to inconsistencies in detecting MUC1 in diverse cancer types and within different cases of the same disease." (PMID 40179083, 2025). "MUC1, however, was found to be a potential anti-neoplastic antigen because of its change in the expression profile of normal and cancer cells, and it has been identified by the American Cancer Institute Working as one of the most promising cancer vaccine-targeted antigens in clinical trials." (PMID 40001578, 2025). "TG4010 is designed to stimulate a targeted immune response against cancer cells expressing MUC1." (PMID 41303538, 2025). "Aptamer-based optical biosensors utilizing colorimetric and fluorescent responses have demonstrated significant potential for detecting MUC1, a critical cancer biomarker, by integrating the specific recognition capabilities of aptamers with visually or spectroscopically detectable signals." (PMID 40363817, 2025). "MUC1 has emerged as another promising target in cancer immunotherapy." (PMID 40149002, 2025). "Further research delved into the roles played by MUC1 in advancing cancer." (PMID 40699746, 2025). "Thus, cancer vaccines based on MUC1 have been developed and tested in clinical trials, with some success in diminishing tumour load." (PMID 41011627, 2025). "Aberrant expression of MUC1 has been demonstrated to play a seminal role in cancers, including MM." (PMID 40179083, 2025). "Furthermore, MUC1’s capability to create a supportive microenvironment enables cancer cells to evade the initial signals that would otherwise activate apoptotic pathways." (PMID 40655139, 2025). "Similarly, MUC1 has emerged as a viable drug target for many cancers due to its oncogenic nature and increased expression in most cancer types, including BrCa." (PMID 41471303, 2025). "TACAs of MUC1 have been considered crucial targets for cancer vaccination development." (PMID 41154387, 2025). "Additionally, MUC1 was involved in important functions enabling cancer spread and overall cell aggressiveness." (PMID 40610411, 2025). "In addition to MUC4, Gal-3 is also a ligand for MUC1 in epithelial cells, which induces MUC1 cell surface polarization, increased cancer cell aggregation, and adhesion to vascular endothelium." (PMID 40699805, 2025). "However, membranous MUC1 weakly correlated with Ki‐67 in all carcinoma cells (ρ = 0.215, p = 0.024) and solid structures (ρ = 0.349, p = 0.011), but not in MIPs (ρ = −0.027, p = 0.814) or cribriform structures (ρ = 0.169, p = 0.087)." (PMID 41332218, 2025).
cancer (continued). "However, cases with a high Total AR areal density (> 6.86/mm2) showed elevated cytoplasmic MUC1 in overall carcinoma cells, MIPs, and cribriform structures (p = 0.026–0.048), but not in solid structures." (PMID 41332218, 2025). "MUC1 is widely studied for its role in distinct types of cancers." (PMID 38540735, 2024). "MUC1 overexpression can enhance cancer cell proliferation by modulating cell metabolism." (PMID 38540735, 2024). "Additionally, investigations of membrane-bound mucin genes (MUC1, MUC3, MUC4, and MUC13), associated with altered O-linked glycosylation in various cancers, were investigated through the GEO database (GSE16581) and underwent qPCR." (PMID 38274327, 2024). "Combined treatment with standard anticancer therapy and the WT1/MUC1-DC vaccine may induce antitumor immune responses during vaccination and appears to provide some clinical benefit to patients with cancer." (PMID 38336778, 2024). "Cancer cells in the MUC1-KO group lost the ability to metastasize to the lung." (PMID 38702644, 2024). "MUC1 is a cell membrane glycoprotein that is also overexpressed in NSCLC and has been implicated in the carcinogenesis of premalignant lung lesions; thus, MUC1 has been used as a target for cancer vaccine strategies." (PMID 38336778, 2024). "On the other hand, VIM+ CAFs may facilitate the EMT function of MUC1+ cancer cells through the MK pathway." (PMID 39422697, 2024). "MUC1, a transmembrane protein, plays a crucial role in cancer cell adhesion and metastasis." (PMID 38622705, 2024). "Moreover, numerous studies have shown that MUC1 is an oncogene, making it an attractive target for cancer immunotherapy." (PMID 39491020, 2024). "Thus, the data are in line with previous findings that MUC1 CT enhances STAT3 activation in cancer cells." (PMID 38326371, 2024). "Mucin 1 (MUC1) is overexpressed in various cancers and contributes to tumorigenesis in HCC." (PMID 39569202, 2024). "Taken together, the present study demonstrated a novel regulatory MUC1/ERK/ITGA2/3 pathway and MUC1 may be used as a potential biomarker for early detection of cancer and therapeutic target in CSCC." (PMID 38702644, 2024). "Furthermore, MUC1 contributes to the self renewal and maintenance of the cancer stem cell (CSC) populations that are known to be involved in mediating resistance to chemotherapy." (PMID 38254882, 2024). "However, MUC1 promotes cancer invasion, metastasis, and neovascularization when it is expressed in cancer cells." (PMID 39835140, 2024). "In fact, we demonstrate that the conditioned medium collected from mast cells is able to increase the capability of cancer cells to form mammospheres in a MUC-1/estrogen receptor-dependent manner, and the whole mechanism can be prevented by inhibiting heparanase." (PMID 39349458, 2024). "The interaction between microbes and MUC1 offers a glimpse into the biochemical modifications of the proteins involved, which could serve as targets to inhibit the development of cancer." (PMID 38886669, 2024). "This review summarizes recent findings on the structure of MUC1, its expression in different tumors and its involved mechanism pathways, with emphasis on new progress in cancer therapy which related MUC1 in the past decade and evaluates their therapeutic effect." (PMID 38164273, 2024). "Furthermore, the effectiveness of this nanosensor was verified by mapping the spatial expression of MUC1 in cancer cells, and it was found to have excellent sensitivity." (PMID 38338846, 2024). "Also, MUC1-overexpressed cancer cell lines are preferentially killed by a DNA-PK inhibitor and HDAC1/2 inhibitors." (PMID 38927743, 2024). "Additionally, MUC1 enhances the stemness of cancer cells, primarily by activating pluripotency networks and also playing a role on the outer mitochondrial membrane, reducing drug-induced mitochondrial pro-apoptotic factor release and apoptosis." (PMID 38361923, 2024).
cancer (continued). "We found that higher expression of MUC1 increased the sensitivity of cancer cells to Napabucasin." (PMID 38326371, 2024). "MUC‐1 has been reported to be overexpressed in various cancer tissues." (PMID 39118454, 2024). "Additionally, Tmunity Therapeutics recently registered a phase I trial to test the safety, tolerability, feasibility, and preliminary efficacy of MUC1 targeted CAR-T cells (TnMUC1) in TnMUC1-positive advanced cancers, including NSCLC (NCT04025216)." (PMID 38475858, 2024). "Tracing the evolutionary trajectory of epithelial cells unveiled the terminally differentially MUC1+ cancer cells with a high epithelial‐to‐mesenchymal transition potential, and they demonstrated spatial proximity with fibroblasts and endothelial cells, correlating with poor prognosis." (PMID 39422697, 2024). "In an alternative strategy, the Tn antigen was first conjugated to an unnatural amino acid, α-methylserine, and the glycosylated α-methylserine was incorporated into the most immunogenic region of the protein mucin 1 (MUC1), which is overexpressed on the surface of cancer cells." (PMID 39591192, 2024). "MUC1 is a transmembrane glycoprotein that is overexpressed in many cancers, including NSCLC." (PMID 38475858, 2024). "Moreover, MUC1 is involved in cancer invasion, metastasis, angiogenesis, and the regulation of related biomolecules." (PMID 39337716, 2024). "Mucin1 (MUC1) has been identified as a tumor-associated antigen (TAA) that is intricately linked with the invasive and metastatic capabilities of cancerous cells across a variety of cancers, including TNBC." (PMID 38612592, 2024). "The shared expression of the Tn-MUC1 glycoform across several cancer types could enable Tn-MUC1.CAR-T cells to recognize and kill multiple different tumors while maintaining a favorable safety profile." (PMID 38887285, 2024). "Furthermore, the reported positivity rates of MUC1 in AoV cancer vary widely, ranging from 70% to 100%, complicating its use as a prognostic value." (PMID 38893239, 2024). "Moreover, MUC1 was particularly overexpressed in sarcomatoid components, corresponding to the areas in which the cancer cells had undergone epithelial-mesenchymal transition." (PMID 38540735, 2024). "MUC1 can interfere with immune recognition and destruction of cancer cells." (PMID 39766805, 2024). "In addition, MUC1 was able to enhance the invasiveness of cancer cells by inducing the transformation of the epithelial mesenchymal (EMT)." (PMID 38517922, 2024). "We first verified whether cancer cell treatment with mast cell conditioned medium was able to increase the expression levels of Muc1 in spheres, finding a modest increase partially prevented by OGT2115." (PMID 39349458, 2024). "For this reason, MUC‐1 has been the focus of attention by researchers in cancer treatment." (PMID 39118454, 2024). "Finally, in CRC several TAAs target of autoantibodies have been widely explored in clinical trials as cancer vaccines as CEA, and MAGE, together with other pan-explored TAAs in different cancers as MUC1, EGFR, or Survivin." (PMID 39234247, 2024). "The presence of naturally occurring anti-MUC1 antibodies specific for the unglycosylated peptide backbone epitopes has been correlated with better disease prognosis and serves as a well-established biomarker for multiple cancer types." (PMID 39449327, 2024). "The overexpression of MUC1 contributes to the drug resistance in several cancer types." (PMID 38702644, 2024). "To test our idea that MUC1 could represent the link between mast cells and cancer cell estrogen receptor up-regulation, we silenced Muc1 expression in PyMT41c cells which were then co-cultured together with mast cells." (PMID 39349458, 2024). "Notably, a cancer-specific glyco-epitope on the Muc1 protein (Tn-Muc1) has been demonstrated as an excellent target for CAR T cells against several types of cancers." (PMID 38549116, 2024).
cancer (continued). "Additionally, Apt-PEG-AuPAMAM-CUR significantly increased curcumin’s cancer cell toxicity by binding to MUC-1 cancer cells, which enhances receptor-mediated endocytosis." (PMID 38399238, 2024). "MUC1 expression is stimulated by inflammation and we hence hypothesized that mast cells could be responsible for its upregulation in cancer cells." (PMID 39349458, 2024). "Furthermore, MUC1 promotes cancer cell survival in hypoxic and nutrient-deprived environments by regulating autophagy, reactive oxygen species levels, and metabolite flux." (PMID 38540735, 2024). "In cancer cells, MUC1 often undergoes aberrant glycosylation and overexpression." (PMID 39372036, 2024). "As CEACAM6 has been less studied in cancer compared to MUC1, we chose CEACAM6 for further studies." (PMID 39468006, 2024). "Additional studies have found that the degree of glycosylation of MUC1 may be critical to its role in cancer." (PMID 38539529, 2024). "Either MUC1 or FGF7 knockdown impeded the migration‐promoting function of cancer cells and CAFs." (PMID 38778448, 2024). "Furthermore, saliently enhanced expression levels of MMP7 and SDC1, which correlated with extracellular matrix remodelling, in MUC1+ cancer cells within the chemotherapy cohort was discovered, further supported by the GSVA findings." (PMID 39422697, 2024). "MUC1 was also proved to interact with different effectors such as β-catenin, receptor tyrosine kinases, and cellular-abelsongene, which were important in the pathogenesis of cancers." (PMID 39886661, 2024). "FA12 peptide and AR13 peptide are used for targeting cancer cells overexpressing Muc1." (PMID 38543324, 2024). "Additional studies have shown that MUC1 overexpression by cancer cells is associated with protection from natural killer cells (NK cells), cytotoxic T cell-mediated lysis, and TRAIL- and Fas ligand-induced apoptosis, suggesting that MUC1 contributes to immune evasion in aggressive cancer." (PMID 38540735, 2024). "Expression and oncogenic roles of MUC1 in various human cancers." (PMID 38361923, 2024). "Intracellular uptake experiments confirmed the hypothesis that Nio/Dox‐Cis/MUC‐1 niosomes exhibit enhanced internalization by cancer cells specifically expressing MUC‐1, thereby validating the targeted approach." (PMID 39118454, 2024). "MUC1 has been shown to interact with diverse effectors such as β-catenin, receptor tyrosine kinases, and cellular-abelsongene, which are of importance in the pathogenesis of various malignant tumors." (PMID 38164273, 2024). "In this study, we focus on recent evidence suggesting that STAT3 and MUC1 regulate each other’s expression in cancer cells in an auto-inductive loop and found that their interaction plays a prominent role in mediating epithelial-to-mesenchymal transition (EMT) and drug resistance." (PMID 38326371, 2024). "MUC1 was detected in EV-free plasma from cancer patients and healthy control samples." (PMID 39061213, 2024). "In addition, higher levels of serum CA 15-3 (the soluble form of MUC1) were identified in patients with reduced cancer-specific (CSS) and progression-free survival (PFS)." (PMID 36902242, 2023). "Thus, pulsing target cells with the inhibitor compounds induced the truncated cancer-associated O-glycan Tn29,63, which triggered ADCC activity by mAbs directed to Tn-glycopeptide epitopes in MUC1 and FXYD5." (PMID 36804936, 2023). "It would be highly desirable to develop an effective therapy against MUC1-expressing cancers." (PMID 37489369, 2023). "Therefore, they conceived the idea of decorating the surface of RBC-derived nanobubbles with an aptamer developed against MUC1, a glycoprotein overexpressed in several types of cancer, including colorectal cancer." (PMID 37242687, 2023). "Thus, the influence of MUC1/T antigen—galectin-3 interactions on cancer development raises promising therapeutic strategies involving the inhibition of such interactions." (PMID 37345016, 2023).
cancer (continued). "Merit of antibody interacting simultaneously with MUC1 TRD having cancer-specific Tn and core 1 type O-glycans including T and ST antigens is clear because human normal cells have been known to express MUC1 modified dominantly with mature and complicated core 2 type O-glycans." (PMID 37547453, 2023). "Overexpression of the transmembrane glycoprotein MUC1 is also observed in many types of cancers." (PMID 37243023, 2023). "MUC1 is also aberrantly glycosylated, which exposes various antigens, thereby generating a new set of antibodies that can prove beneficial in the diagnosis of cancer." (PMID 37443570, 2023). "Hence, we tested the effect of siRNA-induced MUC1 silencing in cancer cells by our P. aeruginosa adhesion assay." (PMID 36609683, 2023). "In addition, MUC1 is also a natural ligand for Gal-3, and the interaction of Gal-3 with MUC1 promotes the adhesion of already disseminated cancer cells to the endothelium of blood vessels, thus metastasis." (PMID 37894512, 2023). "Thus, Tn-MUC1 is a promising target currently explored in cancer immunotherapies by mAbs or CAR-T cells with high affinity for this mucin glycoform." (PMID 36804936, 2023). "Another marker often used in clinical practice to identify cancer cells is CA19-9/MUC1." (PMID 37813486, 2023). "The MUC1 expression in cancer cells might only be affected by the cellular response to radiotherapy but not affected by TAM stimulation." (PMID 36688997, 2023). "MUC1-CT has become a promising druggable target for treating cancer patients in preclinical models." (PMID 36810913, 2023). "The “Protective shield” of MUC1 may be broken, smaller cell surface adhesion ligands can be revealed, and cancer-endothelial adhesion can be enhanced, which can lead to promoting metastasis." (PMID 37345016, 2023). "An increase in the expression of MUC1 on the surface of cancer cells could speed up the metastasis of those cells because CA15-3 is involved in cell-to-cell contact and cellular adhesion." (PMID 36619680, 2023). "Indeed, many cell membrane glycoproteins, for example integrins and MUC1 which are known to be involved in cancer progression, showed glycosylation changes in response to C1GalT1 suppression in this study." (PMID 37612278, 2023). "MUC1 interacts with neutrophils and macrophages to protect cancer cells during metastasis." (PMID 36738352, 2023). "In this work, MUC1 aptamer could specifically target MUC1 protein overexpressed on cancer cell membranes and the sequence of T22‐NLS peptide could bind affinity with CXC chemokine receptor (CXCR4)." (PMID 36654533, 2023). "The obtained antibodies were able to recognize MUC1-positivebreast cancer cells." (PMID 37279388, 2023). "Aberrant expression of the membrane-bound form of mucin, MUC1, and the secreted form of mucin, MUC2, may be associated with cancer growth, differentiation, transformation, and invasion." (PMID 37337182, 2023). "Stimulate an antigen-specific cellular immune response against MUC1+ cancer cells." (PMID 37492478, 2023). "MUC1 is a membrane-bound mucin, which shows increased expression in various human cancers." (PMID 37544972, 2023). "In addition, EBV latent membrane protein 1 (LMP1) can activate STAT signaling by regulating MUC1 expression, which ultimately promotes cancer invasion and metastasis." (PMID 37894512, 2023). "In cancers located in other tissues, different aberrant glycosylation of MUC1 occurs." (PMID 37455827, 2023). "In conclusion, this investigation has provided the first unbiased discovery of a novel pathway mediated by TG2 via MUC1, which is shown to contribute to androgen insensitivity and malignancy of PCa cells and be upregulated in PCa biopsies, with potential relevance to cancer immune evasion." (PMID 37160910, 2023). "The extracellular domain of MUC1 contains a variable region of twenty amino acid tandem repeats (HGVSTAPDTRPAPGSTAPPA) with five potential O-glycosylation sites that become exposed in cancer cells." (PMID 36851313, 2023).